HIF1A (hypoxia inducible factor 1 subunit alpha)
Diseases named in the same sentence as HIF1A in open-access papers (continued):
Sharing a sentence is not in itself a finding about the gene and the disease.
colorectal cancer (continued). "In human colorectal cancer cells, tanshinone IIA restrained β-catenin/VEGF-mediated angiogenesis by targeting transforming growth factor-β (TGF-β1) in normoxic and hypoxia-inducible factor 1α (HIF-1α) in hypoxic micro-environments." (PMID 35897965, 2022). "miR-93-5p could regulate HIF-1A/AXL signaling pathways to facilitate the progression and EMT of colorectal cancer." (PMID 34790052, 2021). "Besides, SNHG11 was shown to be upregulated in colorectal cancer and blocked the interaction between pVHL and HIF-1α via binding to HIF-1α, preventing HIF-1α ubiquitination and degradation." (PMID 34699314, 2021). "Moreover, ilexgenin A inhibits HIF-1α expression, consequently downregulating sterol regulatory element-binding transcription factor 1 (SREBF1) expression and lipid accumulation in colorectal cancer cells." (PMID 34575983, 2021). "Previous in vitro study in colorectal cancer cells treated with CT showed decreased cell invasion, and in vivo CT treatment decreased colorectal cancer tumor size, promoted downregulation of PI3K/Akt/mTOR signaling and inhibition of HIF-1α factor." (PMID 33544704, 2021). "Not surprisingly, imperatorin decreases the growth of colorectal cancer and the tissue expression of HIF-1α and VEGF in vivo." (PMID 34575983, 2021). "To test whether Smurf2 affects the level of HIF-1α, we transfected the HCT116 colorectal cancer cells with a Smurf2-targeting siRNA to decrease its expression." (PMID 34611473, 2021). "Moreover, 36 colorectal cancer tissues and their adjacent normal tissues were obtained to determine the mRNA content of AXL and HIF‐1A." (PMID 32061057, 2020). "A mechanism was established by which the miR-1/Smad3/HIF-1α axis facilitates the Warburg effect to promote CRC progression in vitro and in vivo, showing the potential role of miR-1 in molecular therapy of patients with advanced colorectal cancer." (PMID 32309224, 2020). "Additionally, the expression of Ki67 combined with HIF-1α and CK20 was predicted to be as prognostic biomarkers in the microenvironment of colorectal cancer tissue." (PMID 30341240, 2018). "In addition, HIF-1α promotes EMT and cancer metastasis by binding to the promoter of ZEB1 in colorectal cancer." (PMID 30671168, 2018). "Moreover, we showed that the high expression of RPS7 and low-expression of HIF-1α were significantly associated with good progression-free and/or overall survivals in stage IV CRC patients, which may be used as potential markers for diagnosis and clinical treatment of advanced colorectal cancer." (PMID 26735579, 2016). "Ten human colorectal cancer cell lines and other types of cancer cell lines including HeLa (cervix), A549 (lung), PC3 (prostate) and U87-MG (brain) exhibited similar NQO1-mediated HIF-1α induction in both normoxia and hypoxia." (PMID 27966538, 2016). "Previously, we developed HIF-1α inhibitor LW6 from an aryloxyacetylamino benzoic acid scaffold and showed that LW6 inhibits accumulation of HIF-1α and expression of its target genes in colorectal cancer cells." (PMID 27611801, 2016). "It was shown in vitro by Western blot, flow cytometry, and ELISA that bortezomib accumulated HIF-1α in non-functional forms and blocks its hypoxia response in human colorectal cancer cell lines." (PMID 26416246, 2015). "HIF-1α and CXCR4/CXCL12 have crucial roles in the metastatic process of colorectal cancer." (PMID 24629239, 2014). "Our results indicate that FDG uptake associated significantly with hypoxia, reflected by HIF1α expression, but not with proliferative activity, reflected by PCNA expression; these gastric cancer findings correspond to our previous report on colorectal cancer." (PMID 23718763, 2013). "HIF-1α and HIF-2α expression and clinicopathological features for colorectal cancer." (PMID 24324596, 2013). "Moreover, HIF-1α was shown to directly bind to the COX-2 promoter, thereby regulating the expression of COX-2 protein in two colorectal carcinoma cell lines, HCT116 and HT29." (PMID 24194783, 2013).
colorectal cancer (continued). "So far, detailed studies about the role of HIF-1α in the development of colorectal cancer do not exist." (PMID 18983642, 2008). "Therefore, we propose a novel mechanism of colorectal tumorigenesis via HIF1α regulation by TRIM1, which could potentially give rise to a new strategy for treating colorectal cancer." (PMID 38769340, 2024). "In breast and colorectal cancer cells, NRF2 silencing increased miR-181c-5p expression levels, subsequently suppressing mitochondrial respiration and O2 consumption by targeting the complex IV subunit, ultimately preventing HIF-1α accumulation under 24-h hypoxic conditions 64,65." (PMID 38424190, 2024). "As expected, the level of HIF-1α, Lon, ULK1, and ULK1 downstream autophagy proteins, ULK1-S555 phosphorylation, ATG13, and FIP200, was increased under hypoxia exposure or CoCl2 treatment in HCT-15 colorectal cancer cells and in FADU, HSC-3 and OEC-M1 oral cancer cells." (PMID 36927870, 2023). "However, our findings contrast with those of Kim's study, which reported no physical interaction between VBP1 and HIF-1α in human colorectal carcinoma HCT116 cells." (PMID 37201586, 2023). "Another study also showed that miR-103a-3p knockdown suppressed HIF1A expression by targeting the core molecules LATS2 and SAV1 of the Hippo/YAP1 pathway, contributing to reduced proliferation, invasion, migration, glycolysis and angiogenesis in colorectal cancer." (PMID 35094292, 2022). "Interestingly, LH2 is a novel regulator to promote the aerobic glycolysis and tumor progression in the colorectal cancer by upregulating hexokinase 2, as LH2 is regulated by HIF-1α, which may mediate the aerobic glycolysis." (PMID 35559258, 2022). "In addition to lung and colorectal cancer, oncogenic KRAS could also facilitate HIF-1α activation and promote pancreatic tumor growth under hypoxic conditions." (PMID 36550998, 2022). "However, colorectal cancer cell lines with KRAS/BRAF mutations exhibited increased GLUT1 expression, independent of HIF1α status in normoxic conditions." (PMID 33420213, 2021). "As AMBRA1 affected CTNNB1 transcription via ALDH1B1, which is a crucial CSC marker of colorectal cancer, we next investigated whether AMBRA1 expression affects the mRNA levels of several CSC-related β-catenin target genes, including LGR5, HIF1a, ALDH1A3, CD24, and SOX4." (PMID 34769507, 2021). "Hypoxia-inducible factor (HIF-1α) has been shown to synergize with CAFs paracrine signals, namely TGF-β2, to activate hedgehog transcription factor GLI2 in cancer stem cells (CSCs), leading to enhanced stemness/dedifferentiation and intrinsic resistance to chemotherapy of colorectal cancer." (PMID 34095111, 2021). "Expression of HIF-2α induces colorectal cancer, but HIF-1α does not." (PMID 33519819, 2020). "Furthermore, PTBP3 overexpression in human colorectal cancer has been demonstrated to enhance the expression of a cancer progression factor, the hypoxia-inducible transcription factors 1α (HIF-1α), by directly binding to the HIF-1α 5’UTR mRNA." (PMID 32276354, 2020). "Taken together, these results verified that AAM effectively inhibits migration and VM formation by suppressing the ROS/HIF-1α/MMP2 pathway in colorectal cancer under hypoxic condition, suggesting AAM could serve as a therapeutic agent to inhibit VM formation in human colorectal cancer." (PMID 32499699, 2020). "Additionally, this research group demonstrated the importance of ZEB1 in HIF-1α induced metastasis with higher percentage of HIF-1α and ZEB1 positive staining and lower percentage of E-cadherin positive staining in patients' metastatic lymph nodes compared with primary colorectal cancer tissues." (PMID 32322559, 2020). "Similarly, overall survival in colorectal cancer patients was significantly different between patients positive for HIF-1α and patients negative for HIF-1α (P=0.040)." (PMID 24260057, 2013).
colorectal cancer (continued). "However, in multivariate Cox model analysis, HIF-1α was not an independent prognostic factor for the overall survival of colorectal cancer patients." (PMID 24260057, 2013). "However, a potential activation of HIF-1α in colorectal carcinoma cells after exposure to LPS has not been reported." (PMID 18983642, 2008). "To examine whether HIF-1α can influence the progressive behavior of colorectal carcinomas, we compared its expression in non-metastatic and metastatic malignant cases." (PMID 18983642, 2008). "However, evidence could not be found for the correlation between HIF-1α expression and the amount of stroma in colorectal cancers." (PMID 33810015, 2021). "Taken together, our data revealed the negative correlation between RPS7 and HIF-1α, and they modulate the glycolysis of colorectal cancer through molecules including GLUT4 and LDHB, which may represent novel prognostic markers and/or therapeutic targets for colorectal cancer." (PMID 26735579, 2016). "In colorectal cancer, shikonin inhibited HIF-1α protein synthesis without affecting the expression of HIF-1α mRNA or degrading HIF-1α protein, which leads to inactivation of mTOR/p70S6K/4E-BP1/eIF4E." (PMID 38001865, 2023). "Paradoxically, a recent proteomic analysis in a colorectal cancer cell line revealed that lipogenic enzymes are suppressed in a HIF-1α dependent manner, suggesting that HIF-1α does not necessarily facilitate lipid biosynthesis." (PMID 27589734, 2016). "Notably, HIF-3α1, but not HIF-1α, has been shown to upregulate genes in the Janus kinase-signal transducer and activator of transcription (JAK-STAT) signaling pathway, which is critical in promoting carcinogenesis in colorectal cancer tissues." (PMID 38020884, 2023). "miR-24/VHL/HIF-1α forms a double-negative feedback regulatory pathway that can enhance the effect of HIF-1α and miR-23a ~ 27a ~ 24 cluster, greatly regulating the metabolic network of colorectal cancer and shifting the metabolic balance of normal cells to glycolysis." (PMID 33109235, 2020).
melanoma (379 papers, 2004 to 2026). A malignant, usually aggressive tumor composed of atypical, neoplastic melanocytes. "Our qPCR results showed that supernatants from the drug-treated groups significantly downregulated VEGFA and HIF-1α expression, thereby exacerbating the deficiency of oxygen and nutrients within the melanoma." (PMID 41596235, 2026). "The results revealed that melanoma cells exhibited substantial expression of critical stemness-associated genes, namely HIF1A, EPAS1, TWIST1 and EZH2." (PMID 41383633, 2025). "The zinc finger protein 292 (ZNF292) gene was reported to be a target gene regulated by HIF1α in melanocytes whose gene expression change under hypoxia and was associated with primary human melanoma tumours." (PMID 39199954, 2024). "Dual inhibition of PGC1α and HIF1α causes energetic deficits, but partial rescue of melanoma cells have been observed through glutamine utilization." (PMID 38774408, 2024). "It is likely that HIF-1α regulation by BRAF is not limited to melanomas and is equally present in other cancers with BRAF mutations." (PMID 36901857, 2023). "Consistent with our in vitro observations, loss of HIF‐1α in NK cells leads to increased pulmonary metastasis of intravenously injected melanoma cells." (PMID 36987917, 2023). "L1CAM expression in primary melanoma was significantly associated with HIF-1α expression (p < 0.0001) and sentinel lymph node metastasis (p = 0.011)." (PMID 36142656, 2022). "In contrast to our previous findings in a TCGA pan-cancer cohort, patients with melanoma in the CCND1 High Amplification group in the present study showed downregulation of many genes associated with angiogenesis (HIF1A, VEGFs, VEGFRs, FGFs, and FGFRs)." (PMID 35844619, 2022). "Activation of the mitogen-activated protein kinase/extracellular signal-regulated kinase (MAPK/ERK) pathway in BRAF-mutated melanoma cells, as A375 cells, can promote hypoxia inducible factor-1 alpha (HIF1α) expression, hence leading to a high glycolytic rate." (PMID 35163570, 2022). "Mechanistically, PARP1 is associated with the stabilizing of HIF-1α, which plays a vital role in melanocyte transformation and represents an essential feature in malignant tumor growth, including melanoma." (PMID 36588679, 2022). "HIF-1α-induced expression of AKAP12v2 (A-kinase anchor protein 12 variant 2) was shown to promote migration and invasion of melanoma cells." (PMID 33918883, 2021). "The HIF-1α-induced overexpression of antiapoptotic protein Mcl-1 (myeloid cell leukemia 1) was also observed in BRAF-mutated melanoma cells." (PMID 33918883, 2021). "Activation of AP-1 is critically linked with Ras-induced oncogenic transformation in melanoma cells and tightly regulates the expression levels of both HIF-1α and MMPs metastatic promoters." (PMID 34764332, 2021). "An extensive list of transcription factors has been directly linked with metabolic plasticity during melanoma metastasis and adaptive resistance to MAPKi (HIF1α, MYC, MITF, PGC1α, PPARα, TFAM)." (PMID 34830962, 2021). "For example, miR-210, a signature of hypoxia in many cell types and a robust target of HIF-1α, decreases the susceptibility of lung cancer and melanoma cells to CTL-mediated lysis, through the down-regulation of different cancer cell genes." (PMID 33066331, 2020). "HIF-1α overexpression is associated with tumor aggression for several types including glioblastoma, oligodendroglioma, melanoma, breast, cervical, colon, ovarian, endometrial, lung, prostate, bladder, pancreatic, and oropharyngeal cancer." (PMID 32973969, 2020). "Higher expression of HIF1α, and lower expression of bFGF in the melanoma compartment are associated with longer OS." (PMID 33552976, 2020). "Our results also show that the molecular mechanism underlying miRNA-138 action in melanoma inhibits cell proliferation and metastasis by directly targeting degradation of HIF1α." (PMID 31371307, 2019).
melanoma (continued). "Inhibition of OXPHOS through suppression of PGC-1α led to loss of viability in melanoma cells, which was then rescued by HIF-1α-mediated activation of glycolysis." (PMID 30771209, 2019). "This is consistent with our findings of stimulating effects of Metformin on VEGF and HIF-1α in WM35 melanoma, since this cell type exhibits the BRAF-V600E-mutation." (PMID 28278159, 2017). "It has been reported that HIF1α and HIF2α are involved in invasion and invadopodia formation and associated with melanoma metastases in patients." (PMID 28137308, 2017). "The expression levels of CCL2 and HIF1A were positively correlated in BRAF-mutated melanoma tumor specimens, further supporting an association between HIF1 and CCL2." (PMID 26684239, 2016). "By inhibiting oxygen-sensitive prolyl hydroxylases (PHDs) with DMOG, we observed that the resulting increased stabilization of HIF1α was associated with a higher HMGB1 release in melanoma cell lines." (PMID 27426915, 2016). "One study showed that under normoxia, arginine-deprivation inhibited basal HIF-1α expression in ASS1-deficient melanoma cells." (PMID 26972697, 2016). "Overexpression and stabilization of HIF-1α has been identified in numerous malignancies, including melanoma, and has been implicated in driving its progression and metastatic potential." (PMID 26547841, 2015). "ROS-generating CM of mutated fibroblasts promoted metastasis of A375 melanoma through the increasing of ROS and HIF1-α stabilization in melanoma cells." (PMID 23937926, 2013). "Whereas HIF-1α expression has been associated with decreased survival in cancers of the breast and other sites, little is known about its role in melanoma." (PMID 19061491, 2008). "In models of melanoma, it was found that HIF-1α activation downstream of melanoma differentiation-associated gene 9 induced expression of IGFBP-2, which promoted endothelial cell migration into the tumor, increasing VEGF-A expression and angiogenesis, enhancing tumor survival." (PMID 41226289, 2025). "A3AR stimulation by Ado causes HIF‐1α overexpression in melanoma cell lines in response to hypoxia." (PMID 40181576, 2025). "Moreover, loss of VBP1 was sufficient for accumulation of HIF1A and HIF1A signalling was further shown to be essential for the acquisition of migratory properties in melanoma." (PMID 38902533, 2024). "Notably, Hif1α or Sox9 expression in melanoma is associated with tumorigenesis, suggesting their putative roles in Bmal1-dependent B16-F10 tumorigenesis." (PMID 38245503, 2024). "Loss of Bmal1 in YUMM2.1 or B16-F10 melanoma cells eliminates clock function and diminishes hypoxic gene expression and tumorigenesis, which could be rescued by ectopic expression of HIF1α in YUMM2.1 cells." (PMID 38245503, 2024). "In addition, Hif-1α and c-Myc crosstalk has been well documented, and the glycolytic phenotype of BRAFV600E-mutated melanoma is known to be directly linked to the increase of Hif-1α and c-Myc TFs, which regulate the expression of metabolic genes." (PMID 37198319, 2023). "Targeting the PI3K/AKT and HIF-1α pathways may be effective for treating melanoma patients with CDKN2A mutations." (PMID 36901857, 2023). "Altogether, HIF-1α expression may be associated with downregulation of PTEN expression in canine melanoma tissue." (PMID 36669005, 2022). "Treatment of mouse melanoma model with isoliquiritigenin, a natural flavonoid compound, caused reduced stability of HIF-1α, responsible for a reduced expression of its target glycolysis enzymes, GLUT 1/4, hexokinase 2, pyruvate kinase M2 and LDHA, finally resulting in induction of apoptosis." (PMID 33964953, 2021). "Constitutive RAS/MAPK/ERK signaling—a hallmark of melanoma—stabilizes HIF1α." (PMID 33870460, 2021). "Moreover, in glycolytic melanomas, HIF1α suppresses transcription of the microphthalmia-associated transcription factor (MITF), which regulates peroxisome proliferator-activated receptor γ 1-α (PGC1α), resulting in OXPHOS inhibition." (PMID 33498757, 2021).